KRAS (KRas proto-oncogene, GTPase)
Description:
Signal transducer in the Ras-MAPK signaling pathway that regulates cell proliferation and survival. Ras proteins bind GDP/GTP and possess intrinsic GTPase activity. Activates MAPK1/MAPK3 resulting in phosphorylation and ultimately degradation of GJA1 (By similarity). Plays a role in promoting oncogenic events by inducing transcriptional silencing of tumor suppressor genes (TSGs) in colorectal cancer (CRC) cells in a ZNF304-dependent manner. Recognized by LZTR1 that mediates its ubiquitination by a BCR (BTB-CUL3-RBX1) E3 ubiquitin-protein ligase complex.
Synonyms: KRAS2; RASK2; KRAS1; K-Ras4B; 'C-K-RAS; C-K-RAS; CFC2; K-RAS2A; K-RAS2B; K-RAS4A; K-Ras; K-Ras 2; KI-RAS; NS; NS3; OES; RALD; RALD2; c-Ki-ras; c-Ki-ras2
Tractability: Small molecule: an approved drug acts on it; a structure with a bound ligand is known; a high-quality ligand is known. Antibody: UniProt places it where antibodies can reach, with high confidence; its Gene Ontology location is reachable by antibodies, with high confidence. PROTAC: it is named in the literature on targeted protein degradation; UniProt records ubiquitination sites on it; ubiquitination databases record sites on it; its protein half-life has been measured; a small molecule that binds it is known.
Target class: Enzyme; Hydrolase
Chemical probes: ACBI3 (high quality), ARS-1620 (high quality), Adagrasib (high quality), BI-0474 (high quality), BI-2852 (high quality), BI-3406 (high quality), FRF-01-116 (high quality), MRTX1133 (high quality), XY-02-082 (high quality), sotorasib (high quality)
Gene: Protein-coding gene on chromosome 12 (25,205,246 to 25,250,936, reverse strand). Ensembl gene ENSG00000133703.
Subcellular location: Cell membrane; Endomembrane system; Cytoplasm; Cell membrane (Isoform 2B)
Subcellular location (Human Protein Atlas): Cytosol
Pathways (Reactome):
Signal Transduction: Activated NTRK2 signals through FRS2 and FRS3; Activated NTRK2 signals through RAS; Activated NTRK3 signals through RAS; Ca2+ pathway; Downstream signal transduction; EGFR Transactivation by Gastrin; Erythropoietin activates RAS; Estrogen-stimulated signaling through PRKCZ; FRS-mediated FGFR1 signaling; FRS-mediated FGFR2 signaling; FRS-mediated FGFR3 signaling; FRS-mediated FGFR4 signaling; GRB2 events in EGFR signaling; GRB2 events in ERBB2 signaling; Insulin receptor signalling cascade; MAP2K and MAPK activation; MET activates RAS signaling; Negative regulation of MAPK pathway; PTK6 Regulates RHO GTPases, RAS GTPase and MAP kinases; RAF activation; RAF/MAP kinase cascade; RAS processing; Regulation of RAS by GAPs; SHC-mediated cascade:FGFR1; SHC-mediated cascade:FGFR2; SHC-mediated cascade:FGFR3; SHC-mediated cascade:FGFR4; SHC-related events triggered by IGF1R; SHC1 events in EGFR signaling; SHC1 events in ERBB2 signaling; SHC1 events in ERBB4 signaling; SOS-mediated signalling; Signaling by SCF-KIT; Signalling to RAS; VEGFR2 mediated cell proliferation; p38MAPK events
Disease: Constitutive Signaling by EGFRvIII; Constitutive Signaling by Ligand-Responsive EGFR Cancer Variants; Constitutive Signaling by Overexpressed ERBB2; Paradoxical activation of RAF signaling by kinase inactive BRAF
and 31 more pathways
Gene Ontology:
Molecular function: GTPase activity; protein binding; protein-containing complex binding; G protein activity; GDP binding; GMP binding; GTP binding; LRR domain binding
Biological process: positive regulation of gene expression; Ras protein signal transduction; MAPK cascade; negative regulation of programmed cell death; positive regulation of cell population proliferation; positive regulation of MAPK cascade; positive regulation of Ras protein signal transduction; positive regulation of TOR signaling; regulation of cell population proliferation; canonical NF-kappaB signal transduction; cardiac muscle cell proliferation; cytokine-mediated signaling pathway; female pregnancy; liver development; myoblast proliferation; positive regulation of cellular senescence; response to glucocorticoid; response to gravity; response to isolation stress; response to mineralocorticoid; signal transduction
Cellular component: cytoplasm; cytoplasmic side of plasma membrane; cytosol; endomembrane system; focal adhesion; GTPase complex; membrane; plasma membrane; protein phosphatase type 1 complex; serine/threonine protein kinase complex; endoplasmic reticulum membrane; Golgi membrane; mitochondrial outer membrane
Genetic constraint (gnomAD): Loss-of-function variants: 1 observed, 18 expected, observed/expected ratio (o/e) 0.0556, 90% interval 0.019 to 0.26. The upper end of that interval is the gene's LOEUF score, 0.26, which puts it in group 1 of 6, group 1 being the genes least tolerant of losing a copy. Missense variants: 83 observed, 203.8 expected, observed/expected ratio (o/e) 0.41, 90% interval 0.34 to 0.49. Synonymous variants: 60 observed, 68.78 expected, observed/expected ratio (o/e) 0.87, 90% interval 0.71 to 1.08.
Gene-disease validity (ClinGen):
ClinGen rates the evidence that KRAS causes each of these diseases.
Noonan syndrome (autosomal dominant): Definitive. Noonan Syndrome (NS) is characterized by short stature, typical facial dysmorphism and congenital heart defects.
cardiofaciocutaneous syndrome (autosomal dominant): Strong. Cardiofaciocutaneous (CFC) syndrome is a RASopathy characterized by craniofacial dysmorphology, congenital heart disease, dermatological abnormalities (most commonly hyperkeratotic skin and sparse, curly hair), growth retardation and intellectual disability.
Costello syndrome (autosomal dominant): Disputed. Costello syndrome (CS) is a rare multisystemic disorder characterized by failure to thrive, short stature, developmental delay or intellectual disability, joint laxity, soft skin, and distinctive facial features.
Cancer hallmarks: tumour promoting inflammation (promotes); change of cellular energetics (promotes); invasion and metastasis (promotes); cell replicative immortality (promotes); escaping programmed cell death (promotes); proliferative signalling (promotes); escaping programmed cell death (suppresses); angiogenesis (promotes)
Homologues: Orthologues: chimpanzee KRAS (90% identical), guinea pig KRAS (90% identical), mouse Kras (90% identical), pig KRAS (90% identical), rat Kras (90% identical), tropical clawed frog krasl (90% identical), rabbit KRAS (90% identical), dog KRAS (89% identical), zebrafish kras (88% identical), macaque KRAS (82% identical). Paralogues in human: HRAS (87% identical), NRAS (85% identical), RRAS2 (57% identical), MRAS (53% identical), RAP1A (53% identical), RRAS (53% identical), RAP1B (52% identical), RALA (51% identical), RALB (50% identical), RIT1 (49% identical), RIT2 (47% identical), ERAS (46% identical), and 23 more.
Diseases named in the same sentence as KRAS in open-access papers:
KRAS is named in the same sentence as 845 diseases in open-access papers, as found by Europe PMC text mining. Sharing a sentence is not in itself a finding about the gene and the disease. The quoted sentences say what the papers report.
colorectal cancer (2,643 papers, 1994 to 2026). A primary or metastatic malignant neoplasm that affects the colon or rectum. "MUTYH‐associated polyposis is an underdiagnosed recessive syndrome that predisposes individual to colorectal cancer and frequently displays KRAS‐G12C mutations." (PMID 41347765, 2026). "Their findings revealed that a higher total vitamin C intake was significantly associated with reduced colorectal cancer-specific mortality in patients with KRAS or BRAF mutations, compared with those with wild-type tumors." (PMID 41403402, 2026). "In conclusions, this study demonstrates that KRAS-mutated colorectal cancer cells develop a hypertranscription phenotype that contributes to aggressive tumor progression." (PMID 41362735, 2026). "Preclinical and clinical evidence supports PLK1 inhibition as a promising therapeutic strategy for KRAS-mutated colorectal cancer." (PMID 41362735, 2026). "Intriguingly, the G12D and G12V KRAS mutations are the most prevalent in colorectal cancer and display the most pronounced changes compared to the milder G12C and WT-like G12A profiles." (PMID 41266617, 2026). "Accurate detection of KRAS codon mutations is essential for precision oncology in colorectal cancer (CRC), yet conventional liquid biopsy methods often lack sufficient sensitivity for rare ctDNA variants, particularly in early diseases." (PMID 42069955, 2026). "Out of the three RAS isoforms (KRAS, NRAS, HRAS), KRAS is the most commonly mutated in approximately 95% of pancreatic cancers, 50% of colorectal cancers and 30% of lung cancers." (PMID 40362630, 2025). "In the 1990s, KRAS mutations were clearly linked to pancreatic (90%) and colorectal cancer (40–50%), emphasizing their role as an oncogenic motor." (PMID 41514544, 2025). "Another study also suggested a higher incidence of KRAS mutations among young adults with colorectal cancer, with an incidence of 50.5%." (PMID 40940860, 2025). "KRAS activation in colorectal cancer is associated with the upregulation of downstream genes such as BCL2, H2AFZ, RAP1B, TBX19, E2F4, and MMP1, many of which are being investigated as markers of clinical progression." (PMID 40906088, 2025). "For example, exosomes from colorectal cancer cells, particularly those harboring KRAS mutations, exhibit distinct miRNA profiles linked to the KRAS gene’s mutation status." (PMID 40141358, 2025). "It maintains the proliferation and survival of colorectal cancer cells with KRAS mutations by promoting the intracellular synthesis of aspartate." (PMID 40298644, 2025). "KRAS mutations lie at the core of colorectal cancer (CRC) pathogenesis, driving persistent activation of the MAPK/ERK and PI3K/AKT pathways and conferring resistance to numerous therapies, particularly anti-EGFR antibodies." (PMID 39941797, 2025). "The clinical implications of KRAS mutations are profound, as they inform treatment strategies and prognostic assessments for patients with colorectal cancer." (PMID 40282985, 2025). "Analogously, in KRAS-mutated colorectal cancer, where ICI is ineffective, expression of key chemokines involved in IFN network signaling, such as CXCL3, are downregulated when KRAS is mutated due to direct interaction with IRF239." (PMID 40442146, 2025). "The cost-effectiveness of treating colorectal cancer patients with mutated KRAS G12C with adagrasib and cetuximab in comparison to adagrasib alone was evaluated in another study." (PMID 41301043, 2025). "Previous studies have shown that PD−L1 expression is inversely correlated with KRAS mutations in colorectal cancer, particularly in MSI−H tumors." (PMID 40547026, 2025). "In CTC screening, common genetic mutations associated with colorectal cancer include KRAS and BRAF mutations." (PMID 40547026, 2025).
colorectal cancer (continued). "Presently, BRAF and KRAS mutations are significant biomarkers in colorectal cancer classification, primarily because they are reliable predictors of treatment response and prognosis, particularly for anti-EGFR therapy." (PMID 40722718, 2025). "This regimen has been FDA approved for advanced colorectal cancer patients with KRAS G12C mutations." (PMID 40303413, 2025). "In KRAS G12C-mutated colorectal cancer, combining MRTX849 with the anti-EGFR antibody cetuximab achieved an ORR of 34%, a DCR of 85%, and a median PFS of 6.9 months, with favorable outcomes and a tolerable safety profile." (PMID 40303413, 2025). "For example, KRAS mutations are found in about 40% of colorectal cancer cases and directly affect the RAS-MAPK signaling pathway, which is responsible for controlling cell growth and division." (PMID 40083375, 2025). "One major direction is broadening the mutation profiles targeted by these assays to include genetic alterations specific to a variety of cancer types, such as KRAS mutations for pancreatic and colorectal cancers or PIK3CA mutations for breast cancer." (PMID 40206799, 2025). "Glecirasib plus cetuximab is under clinical investigation and was approved in a registrational phase III clinical trial in patients with KRAS G12C–mutated colorectal cancer in China." (PMID 40304209, 2025). "Although direct evidence linking estrogen to a higher frequency of KRAS mutations in colorectal cancer remains limited, these mechanistic insights provide a plausible explanation for the observed gender differences." (PMID 40282985, 2025). "LAMA5 is a molecular target of KRAS-mutated colorectal cancer cells and is overexpressed in the tumor microenvironment (TME)." (PMID 38963646, 2025). "KRAS, recognized as one of the most frequently mutated genes in colorectal cancer, significantly influences patient prognosis and survival, and serves as a potential therapeutic target." (PMID 40963625, 2025). "KRAS mutations are among the most prevalent genetic alterations in colorectal cancer, occurring in approximately 30–50% of cases." (PMID 40724985, 2025). "KRAS mutations predominantly occur in lung, pancreatic, and colorectal cancers, while remaining rare in hepatocellular carcinoma (1-3% of cases)." (PMID 40161114, 2025). "Traditional molecular markers such as BRAF and KRAS mutations are widely used in the diagnosis and treatment of colorectal cancer patients." (PMID 40308511, 2025). "The actionable colorectal cancer genes KRAS, NRAS, and BRAF were equally mutated in both phenotypes (q-values: 0.49, 0.97, and 0.97, respectively)." (PMID 40702107, 2025). "Mutations in the KRAS gene have long been implicated in the pathogenesis of colorectal cancer (CRC)." (PMID 40523897, 2025). "Oncogenic KRAS mutations are frequent in colorectal cancer, presenting substantial challenges due to constitutive activation and resistance to molecular-targeted therapies driven by mutation-specific biochemical properties." (PMID 40949096, 2025). "The issue of drug resistance continues to be a major clinical obstacle, affecting roughly 40% of patients with KRAS-mutated colorectal cancer." (PMID 40519270, 2025). "Mutated KRAS is associated with highly aggressive cancers, including pancreatic, lung, and colorectal cancers." (PMID 39858030, 2025). "On the other hand, KRAS gain-of-function mutations are associated with not only colorectal cancer but also pancreatic adenocarcinoma and non-small cell lung cancer." (PMID 40141210, 2025). "Oncogenic KRAS mutations are prevalent in colorectal cancer (CRC) and linked to poor prognosis and therapeutic resistance." (PMID 40131933, 2025). "In one study, among the seven most common KRAS mutations, the c.35G>T (p.G12V) mutation was associated with significantly higher colorectal cancer-specific mortality compared to KRAS wild-type/BRAF wild-type cases." (PMID 40282985, 2025).
colorectal cancer (continued). "In colorectal cancer, a KRAS mutation portends worse survival and a shorter time to recurrence and influences the treatment strategy." (PMID 39851967, 2025). "This article aims to offer an in-depth review of the significance of KRAS mutations in colorectal cancer, exploring their biological implications, clinical relevance, and potential as therapeutic targets." (PMID 39941797, 2025). "KRAS mutations are one of the most dominant mutations in colorectal cancer and are associated with poor prognosis and drug resistance." (PMID 40740271, 2025). "Most TCRs targeting KRAS mutations have been isolated and characterized from TILs or peripheral blood of patients with KRAS-mutant epithelial cancers, mostly colorectal cancers." (PMID 39846249, 2025). "Previous studies have emphasized the intricate role KRAS mutations play in shaping the tumor microenvironment of colorectal cancer." (PMID 39876058, 2025). "KRAS mutations are key drivers of colorectal cancer progression and resistance to treatment, significantly limiting therapeutic options for affected patients." (PMID 39941797, 2025). "In contrast, KRAS G12C mutations are detected in only 3–4% of all colorectal cancer (CRC) cases, representing approximately 6.4% of KRAS-mutated colorectal tumors." (PMID 40940900, 2025). "Through genomic technology, the identification of specific mutations in genes associated with the development of colorectal cancer, such as KRAS, BRAF, and PIK3CA, can be performed." (PMID 40083375, 2025). "Determining the KRAS gene mutation status in colorectal cancer (CRC) before surgery is highly important for an individualized clinical treatment." (PMID 40421293, 2025). "A number of studies have investigated the correlation between KRAS mutations in ctDNA and recurrence following radical resection of colorectal cancer." (PMID 40698441, 2025). "For unexplained reasons, KRAS mutations are predominantly found in pancreatic cancer, colorectal cancer, and adenocarcinoma of the lung, whereas mutated NRAS is predominantly found in a subset of acute leukemias and in myelodysplastic syndromes." (PMID 40694264, 2025). "In a study of rectal cancer, BIK was also identified as a poor prognostic marker for microsatellite-stabilized colorectal cancer harboring KRAS mutations, and rectal cancer patients with high expression of BIK tended to have shorter survival times." (PMID 40438322, 2025). "This inhibitor, called YK1, was shown to be effective in colorectal cancer models with activation of the HER2/KRAS pathway due to oncogenic KRAS G12D mutations." (PMID 41425714, 2025). "In clinical practice, sotorasib (Lumakras) and adagrasib (Krazati) are KRAS G12C inhibitors used in the treatment of advanced colorectal cancer with the KRAS G12C mutation." (PMID 40722718, 2025). "Analysis of a cohort of 10,820 patients revealed that pancreatic cancer exhibited the highest prevalence of KRAS mutations (73.51%), followed by colorectal cancer (41.45%), and lung cancer (11.24%)." (PMID 41184283, 2025). "KRAS G12C mutations are commonly found in lung adenocarcinomas, and G12D mutations are more commonly found in pancreatic and colorectal cancers." (PMID 40362630, 2025). "A descriptive analysis (n = 166) of the mutational frequency in sporadic colorectal cancer was conducted to explore the prognostic implications of KRAS mutations and the BRAF V600E mutation." (PMID 40647370, 2025). "Mutations in RAS genes (NRAS and KRAS) play a significant role in the pathogenesis of colorectal cancer." (PMID 41228322, 2025). "Colorectal cancer-associated genetic alterations, including KRAS mutations, interact with the microbial community, either shaping its composition or being influenced by microbial activity." (PMID 40906088, 2025). "Metastatic colorectal cancer patients who had a high proportion of cell-free DNA and KRAS mutations had a poor prognosis, according to this study." (PMID 40005360, 2025).